SOD3 (superoxide dismutase 3)
Diseases named in the same sentence as SOD3 in open-access papers (continued):
Sharing a sentence is not in itself a finding about the gene and the disease.
Arthritis (6 papers, 2012 to 2025). Inflammation of a joint. "SOD3 reduced arthritis severity in both oxidative burst-deficient Ncf1∗/∗ mice and also in wild-type mice." (PMID 22529530, 2012). "Similarly to the wild-type mice, the difference in the mean arthritis score in NOX2 complex deficient mice was observed when SOD3 was highly expressed from the adenoviral vector." (PMID 22529530, 2012). "The rams suffering from arthritis exhibited abnormally low levels of gene expression for SOD3, CAT, GPX and ATOX1." (PMID 40005882, 2025). "It was found that the adenovirus vector overexpressing SOD3 was directly injected into the paws of neutrophil cytosolic factor 1(Ncf1) (∗/∗) mice with collagen-induced arthritis." (PMID 37759978, 2023). "The results demonstrated that SOD3 reduced the severity of arthritis in Ncf1 (∗/∗) mice and wild-type mice, emphasizing the important role of SOD3 in relieving arthritis in mice." (PMID 37759978, 2023). "Ade-SOD3-treated paws of the Ncf1∗/∗ mice had significantly lower mean disease score than the Ade-LacZ-treated vector control paws at days 24 and 25 after arthritis induction." (PMID 22529530, 2012). "Previous work with collagen-induced arthritis (CIA) suggests that both genetic transfer of the SOD3 gene as well as a small molecular SOD mimetic have the ability to ameliorate arthritis." (PMID 22529530, 2012). "SOD3 is an enzyme that has been shown to give rise to therapeutic responses in damaged tissues such as reduced ischemia-reperfusion injury, arthritis, peritonitis, hind limb injury, and lung injury models." (PMID 22529530, 2012). "Mice started to develop mild, clinically apparent arthritis at day 20 and made a full response, mean arthritis scores reaching 7 (out of the maximum of 15) in Ade-Laz treated and 3 points in Ade-SOD3-treated mice some days later." (PMID 22529530, 2012). "We conclude that the SOD3-mediated anti-inflammatory effect on arthritis and peritonitis operates independently of NOX2 complex derived oxidative burst." (PMID 22529530, 2012). "We confirmed the presence of virally delivered SOD3 mRNA in the paws d25 and thus confirmed that the decrease in arthritis severity coincided with substantial adenovirus driven SOD3 expression." (PMID 22529530, 2012). "The arthritis ameliorating effect of SOD3 was later confirmed using SOD3 knock-out mice." (PMID 22529530, 2012). "Similarly to the wild-type mice, Ade-SOD3 treatment in Ncf1∗/∗ paws induced significantly smaller difference between the virus-treated and PBS-injected paws than Ade-LacZ virus injection (significant d24 and d25 after immunization), again confirming the arthritis limiting effect of SOD3." (PMID 22529530, 2012). "In the current work we studied the role of SOD3 in collagen-induced arthritis (CIA) to understand whether the therapeutic effect of SOD3 on arthritis operates through attenuating the biological effects of the induced oxidative burst produced by the NOX2 complex." (PMID 22529530, 2012). "The expression of the SOD3, CAT, GPX and ATOX1 genes was significantly reduced in the rams with arthritis." (PMID 40005882, 2025). "The SOD3, CAT, GPX and ATOX1 genes were expressed at substantially lower levels in arthritis-affected rams." (PMID 40005882, 2025). "Mice lacking SOD3 display more severe arthritis than that of wild-type mice." (PMID 38802533, 2024). "This research described the antioxidant (SOD3, CAT, GPX, ATOX1 and COX18) and immunological (IL-1α, IL-1β, IL-6, IL-10, TNFα, NCF4, NFKB, TMED, FCAMR and iNOS) genes in rams that had arthritis and those that did not." (PMID 40005882, 2025). "To analyze whether SOD3 can regulate inflammation in the absence of functional NOX2 complex, we injected an adenoviral vector overexpressing SOD3 directly into the arthritic paws of Ncf1∗/∗ mice with collagen-induced arthritis." (PMID 22529530, 2012).
chronic kidney disease (6 papers, 2020 to 2023). Impairment of the renal function secondary to chronic kidney damage persisting for three or more months. "It is possible therefore that felids may have lower levels of SOD1 and SOD3 in their kidney per se, which could predispose them to oxidative damage which, over time, progresses toward chronic renal disease." (PMID 32081923, 2020). "In a previous study, a rise in the plasma SOD3 level and a decline in renal function were closely correlated in chronic kidney disease patients." (PMID 35740095, 2022).
colitis (6 papers, 2013 to 2025). Inflammation of the colon. "Then, SOD3 protein or SOD3-MSCs were administrated into colitis mice to determine their therapeutic efficacy." (PMID 34208517, 2021). "In this study, we suggest SOD3-MSCs as a new therapeutic agent targeting intestinal epithelial recovery in the experimental colitis model." (PMID 34208517, 2021). "Dextran sulfate sodium (DSS)-induced colitis mice received SOD3 or SOD3-transduced MSCs (SOD3-MSCs), and were assessed for severity of disease and junctional protein expression." (PMID 34208517, 2021). "In vivo experiments using a DSS-induced murine model of colitis were also conducted to evaluate the therapeutic efficacy of SOD3 or SOD3-MSCs." (PMID 34208517, 2021). "More interestingly, SOD3 or SOD3-MSCs administration exhibited superior protective effects against colitis symptoms than the infusion of naïve MSCs." (PMID 34208517, 2021). "The activation of the mitogen-activated protein kinase (MAPK) pathway and elevated expression of cytokine-encoding genes decreased in TNF-α-treated Caco-2 cells or DSS-induced colitis mice when treated with SOD3 or SOD3-MSCs." (PMID 34208517, 2021). "HBPF diet also increased the gene expression of Pparg and enzymatic antioxidants (Sod1, Sod3 and Gpx1), genes all reported to be involved in promoting an immunosuppressive Treg cell response and to protect against colitis." (PMID 23776564, 2013). "SOD3 plays a protective role in colitis by scavenging ROS and modulating inflammatory responses." (PMID 40722913, 2025). "Also, we further confirmed that excessive MAPKs activation and increased intestinal permeability were reduced by the treatment with SOD3 or SOD3-MSCs in the DSS-induced colitis model as observed in vitro." (PMID 34208517, 2021). "Therefore, tissue superoxide dismutase (SOD) and catalase enzyme activity was determined in NED-treated DSS colitis animals along with expression of Heme Oxygenase-1 (HO-1) and SOD3 mRNA." (PMID 32650602, 2020). "DSS-induced colitis mice showed increased phosphorylation of JNK and ERK 1/2 and both SOD3 and SOD3-MSCs significantly downregulated the phosphorylation." (PMID 34208517, 2021). "NED treatment also increased HO-1 mRNA (p < 0.05 at 100 mM and p < 0.01 at 150 mM) and SOD3 mRNA expression significantly (p < 0.05 at 100 mM and p < 0.01 at 150 mM) in DSS colitis colon." (PMID 32650602, 2020). "Next, we confirmed the in vivo impact of SOD3, SOD3-MSCs, and MSCs in a DSS-induced colitis model." (PMID 34208517, 2021). "Furthermore, the SOD3-mediated, anti-inflammatory role in skin inflammation by inhibiting the expression of proinflammatory cytokines, including TNF-α, IL-1β, IL-6, and IL-8, and SOD1-mediated suppression of proinflammatory immune responses against oxidative stress in colitis, were also reported." (PMID 40825682, 2025). "Upon colitis induction, the body weight of DSS-fed mice decreased, while that of SOD3 or SOD3-MSCs-injected mice were maintained without a significant loss." (PMID 34208517, 2021).
glioma (6 papers, 2012 to 2025). A benign or malignant brain and spinal cord tumor that arises from glial cells (astrocytes, oligodendrocytes, ependymal cells). "Similarly, individuals with the SOD3 58A allele exhibited a significant association with the risk of glioma occurrence compared to the 58T homozygotes (adjusted OR = 1.64; 95% CI = 1.20–2.23; P-trend < 0.001)." (PMID 23259684, 2012). "In our in-house cohort, the expression levels of CD274, HMGB2, RAC2, RIN3, and SOD3 were elevated in WHO grade IV gliomas compared to grades II/III." (PMID 40852729, 2025). "Before the testing of SOD1 inhibitor on cell survival in glioma, the expression of SOD1, SOD2 and SOD3 in U251 and U87 glioma cell lines was measured." (PMID 35978820, 2022). "Single nucleotide polymorphisms in SOD2, SOD3, GPX1, and NOS1 were found to significantly increase the risk of glioma development in a Chinese population." (PMID 28108734, 2017). "Using single-locus analysis, we identified four SNPs (SOD2 V16A, SOD3 T58A, GPX1 -46 C/T, and NOS1 3’-UTR) that were significantly associated with the risk of glioma development." (PMID 23259684, 2012). "Four SNPs (SOD2 V16A, SOD3 T58A, GPX1 -46 C/T, and NOS1 3’-UTR) demonstrated a significant association with glioma risk, as determined by the dominant model (variant-containing genotypes versus common homozygote)." (PMID 23259684, 2012). "In a study of non-Hispanic whites, an increased risk of glioma was associated with the single nucleotide polymorphism of SOD3." (PMID 28108734, 2017). "U251 and U87 glioma cells expressed high levels of SOD1, low levels of SOD2 and very low levels of SOD3." (PMID 35978820, 2022). "qRT-PCR results showed that these two glioma cell lines expressed higher levels of SOD1, lower levels of SOD2, and very low levels of SOD3." (PMID 35978820, 2022). "We examined 16 single nucleotide polymorphisms (SNPs) of 9 antioxidant genes (GPX1, CAT, PON1, NQO1, SOD2/MnSOD, SOD3, and NOS1*2*3) in 384 glioma and 384 control cases in a Chinese hospital-based case–control study." (PMID 23259684, 2012). "Overexpression of Mn-SOD was shown to prevent this selenite-induced mitochondrial damage in the glioma cells, but in C. elegans overexpression of the SOD-3/Mn-SOD protein did not." (PMID 24406377, 2014). "Notably, IMPA2, SOD3, CD274, ITPRIPL1, and RAC2 displayed relatively negative correlations across multiple cancers, including glioma." (PMID 40852729, 2025).
melanoma (6 papers, 2017 to 2025). A malignant, usually aggressive tumor composed of atypical, neoplastic melanocytes. "In contrast, minor alleles in SOD2 rs8031 (OR 0.16, 95% CI: 0.06 to 0.39; p < 0.001) and SOD3 rs2536512 (OR 0.08, 95% CI: 0.01 to 0.31; p = 0.001) were associated with reduced risk of melanoma." (PMID 29342889, 2018). "Our results highlighted the importance of RAC1, SOD2, and SOD3 variants in the risk of melanoma." (PMID 29342889, 2018). "Though few studies are addressing the role of SOD1 and SOD3 in melanoma, it was shown that SOD1 is involved in melanogenesis and/or differentiation." (PMID 35326089, 2022). "Five SNPs, namely rs1049255 (CYBA), rs4673 (CYBA), rs10951982 (RAC1), rs8031 (SOD2), and rs2536512 (SOD3), exhibited significant genotypic frequency differences between melanoma cases and healthy controls." (PMID 29342889, 2018). "The SOD3 gene was also repressed by CINN-EO treatment in M14 melanoma cells." (PMID 36982774, 2023). "The overexpression of SOD3 inhibited the growth of B16F1 melanoma cells." (PMID 35326089, 2022). "After adjusting for these risk factors, rs1049255 (CYBA), rs4673 (CYBA), rs8031 (SOD2), and rs2536512 (SOD3) were no longer associated with melanoma risk in all three models (p > 0.00238)." (PMID 29342889, 2018). "Therefore, SOD3 repression upon CINN-EO treatment might have exacerbated M14 melanoma cell resistance to the increased superoxide burden." (PMID 36982774, 2023). "Moreover, we found that SOD3 was downregulated in melanoma when compared to nevus." (PMID 35326089, 2022). "In our study, the antioxidant response of M14 melanoma cells to CINN-EO was imperfect, as evidenced by the decreases in OXR1 and SOD3 gene expression." (PMID 36982774, 2023). "From our data analysis, 14% of the melanoma patients showed alteration on the SOD1 gene, 7% on SOD2, and 4% on SOD3." (PMID 35326089, 2022).
Sepsis (6 papers, 2014 to 2024). Sepsis is defined as life-threatening organ dysfunction caused by a dysregulated host response to infection. "EG is important for maintaining normal endothelial function, while it also binds extracellular superoxide dismutase 3 (SOD3) and protects the endothelium from oxidative damage, and inflammatory mechanisms during sepsis degrade pulmonary EG." (PMID 37175583, 2023). "In contrast, at earlier time points after sepsis induction, we demonstrate an increase in SOD3 levels that are properly distributed throughout the lung parenchyma, but this is not sufficient to prevent the formation of peroxynitrite." (PMID 26266917, 2014). "There was no consistent pattern of gene expression; while sod1 and sod2 gene expressions increased 12 h after sepsis, sod3 gene expression decreased at this time point." (PMID 26266917, 2014). "Furthermore, an increase in the immunocontent of SOD2 was observed at all times, and there was an increase in the immunocontent of SOD3 at 6 and 12 h after sepsis induction." (PMID 26266917, 2014). "SOD2 and SOD3 increased after sepsis induction, but this was insufficient to protect the lung." (PMID 26266917, 2014). "Thus, it was hypothesized that endogenous SOD3 could have a major role in lung defenses against oxidative stress during sepsis development." (PMID 26266917, 2014). "Exercise training appeared to normalize antioxidant protein expression in the setting of sepsis (G1 vs. G4 vs. G6) of SOD1, SOD3, and CAT." (PMID 37407986, 2023). "Lung levels of SOD1 decreased 3 and 12 h after sepsis, but SOD2 and SOD3 increased, as well as SOD activity." (PMID 26266917, 2014). "In conclusion, this study demonstrated an increase in SOD3 levels following sepsis; however, this was not able to prevent oxidative stress and inflammation associated with ONOO− production." (PMID 26266917, 2014). "Here, in a CLP model, we demonstrated that during sepsis development, the levels of SOD2 and SOD3 increased in the lung, but these did not prevent nitrosative damage and inflammation." (PMID 26266917, 2014).
anaplastic thyroid cancer (5 papers, 2015 to 2021). "The data therefore suggested a reduced aggressiveness of the anaplastic thyroid cancer cells caused by high SOD3 expression." (PMID 25751262, 2015). "The ability of SOD3 to stimulate the insulin receptor activation is in line with the Gorilla analysis demonstrating a marked enrichment of metabolism-related genes in anaplastic thyroid cancer cells." (PMID 33919252, 2021). "Notably, robust SOD3 over-expression also reduced the rate of cell proliferation of anaplastic thyroid cancer 8505c cells, which lack functional growth-arrest signaling." (PMID 25751262, 2015). "The average SOD3 Log2 median-centered intensity in the normal thyroid is 0.66, which is then decreased gradually, showing the lowest values in PTC (0.15; p < 0.001) and in anaplastic thyroid cancer (0.18; p < 0.001)." (PMID 29478325, 2019). "Inhibition of the kinase had a minor impact on the SOD3 gene expression in human Nthy cells, whereas SOD3 expression was significantly increased in human TPC1 papillary thyroid cancer cells and in human 8505c anaplastic thyroid cancer cells." (PMID 26550576, 2015). "However, the 5-azacytidine treatment significantly increased SOD3 expression in the human papillary thyroid cancer TPC1 and human anaplastic thyroid cancer 8505c cells." (PMID 26550576, 2015). "The results observed in metastatic anaplastic thyroid cancer cells suggest a putative role for the enzyme in GPCR signaling, although currently there are no reports showing SOD3-driven regulation of large G protein signaling." (PMID 29478325, 2019).
diabetic retinopathy (5 papers, 2017 to 2023). "In conjunction with this, a study has shown that exendin-4 can treat diabetic retinopathy by inducing SOD3 promoter acetylation of histone H3 to boost its expression in endothelial cells." (PMID 36831151, 2023). "This study aimed to evaluate the efficacy of SOD3 delivery through an intravitreal route in a rat model of STZ-induced diabetic retinopathy." (PMID 35015779, 2022). "The excess generation of ROS is closely involved in the pathogenesis of diabetic retinopathy (DR); therefore, the maintenance of SOD3 expression at high levels is important for the prevention of DR." (PMID 28751803, 2017).
lung fibrosis (5 papers, 2016 to 2023). "Herein, we analyze the development of PH and lung fibrosis in mice deficient in extracellular superoxide dismutase (SOD3), an enzyme with anti-oxidant activity." (PMID 30453980, 2018). "Interestingly, SOD3-deficient mice develop elevated pulmonary blood pressures and profound vascular wall remodeling when compared to neonatal wild-type littermates in the bleomycin model of pulmonary fibrosis." (PMID 30453980, 2018). "We found that silica exposed Sod3−/− mice developed more lung fibrosis, increased thickening of vascular walls in remodeled pulmonary vessels, and higher right ventricular pressure (RVSP) when compared to wild-type littermate." (PMID 30453980, 2018). "Although the protective role of SOD3 in animal models of lung fibrosis has been reported previously, its contribution to the development of pulmonary vascular remodeling associated with chronic lung diseases is not well understood." (PMID 30453980, 2018). "All of these, except for Prdx6, were highly abundant in BALF of control mice under basal conditions (left-hand panel) and Gpx3 and Sod3 were additionally upregulated in BALF during bleomycin-induced lung fibrosis." (PMID 27435875, 2016). "Our results suggest that SOD3 play an important role in silica-induced lung fibrosis and vascular remodeling in the lung and provides new insight into the role of antioxidant defense mechanisms responsible for protecting the lung from the harmful effects of air pollution and occupational hazards." (PMID 30453980, 2018). "Superoxide dismutase 3 (Sod3), Gpx3, and Gpx activity were increased in mouse BALF during bleomycin-induced lung fibrosis." (PMID 27435875, 2016).
papillary thyroid cancer (5 papers, 2015 to 2025). "To support the signaling data, we tested the effect of SOD3 on cancer cell migration using TPC1 papillary thyroid cancer cells." (PMID 33919252, 2021). "Importantly, a redox gene expression analysis showed downregulation of SOD3 in papillary thyroid cancer TPC1 cells compared to Nthy control cells and upregulation in PTC MCS compared to Thyroid MSCs, hence suggesting autocrine-paracrine conversion of SOD3 mRNA expression." (PMID 28216675, 2017).
Stroke (5 papers, 2017 to 2025). Sudden impairment of blood flow to a part of the brain due to occlusion or rupture of an artery to the brain. "We also observed the downregulation of genes well known to be neuroprotective following stroke such as Sod3 and Bdnf." (PMID 40362325, 2025). "Our study showed that SOD3 was transfected into MSCs, which upregulated the expression of SOD3 in cerebral ischemic tissue, leading to a reduction in infarct volume and ultimately improved neurological recovery in a rat stroke model." (PMID 31461803, 2019). "The goal of this study was to determine whether LIF protects neurons during stroke by upregulating superoxide dismutase 3 (SOD3)." (PMID 26746670, 2017).